KRAS (KRas proto-oncogene, GTPase)
Diseases named in the same sentence as KRAS in open-access papers (continued):
Sharing a sentence is not in itself a finding about the gene and the disease.
ovarian carcinoma (continued). "In the present study, which focused on angiogenesis and inflammation, we established oncogene-transduced mouse ovarian cancer cell lines by transducing c-MYC and KRAS into the mouse ovarian epithelial immortalized cell line, ID8, which has been established from C57BL/6 mice." (PMID 27483433, 2016). "Let-7 suppresses several oncogenes, such as KRAS, HRAS, and c-MYC, in ovarian cancer." (PMID 26779370, 2015). "Active phospho-ERK1/2 was identified in 26 (38.2%) out of 68 type II ovarian carcinomas and did not correlate with KRAS or MAPK1 amplification." (PMID 23820584, 2013). "To further explore the clinical relevance of KRAS or MAPK1 alterations in type II ovarian carcinomas, we identified a correlation between KRAS or MAPK1 amplification or p-ERK protein expression and length of progression-free/overall survival in patients with type II ovarian carcinomas." (PMID 23820584, 2013). "The cell lines did not harbor the most commonly reported KRAS or BRAF mutations nor the most common BRCA1 and BRCA2 mutations identified in the French Canadian breast and ovarian cancer families." (PMID 22931248, 2012). "The obtained data revealed that ovarian cancer patients with more aggressive clinicopathological data, including (advanced stage (III&IV), grade (II), lymph node invasion, big tumor size (T3&T4), and metastatic status (M1), had a remarkably elevation in KRAS expression level." (PMID 40913040, 2025). "The muted effect of the combined treatment on OVCAR3 cells may be due to the amplification of KRAS, unlike the other ovarian cancer cells." (PMID 39625235, 2025). "Driver mutations in KRAS, PIK3CA, PTEN, PPP2R1A, and ARID1A presented as larger clones than non-driver mutations and with similar frequency in lavages from patients with and without ovarian cancer, indicating prevalent somatic evolution in all patients." (PMID 36311816, 2022). "The implications of oncogene expression on cancer drug resistance remain poorly understood, although there have been over 25 oncogenes including KRAS, ERBB2, PIK3CA, AKT hypothesized to contribute to drug resistance in ovarian cancer through various signalling pathways." (PMID 35545786, 2022). "Furthermore, we were able to show that a sequential combination of PLK1i and PARPi enhanced the cellular apoptotic response to carboplatin-based chemotherapy in KRAS-amplified resistant HGSOC cells and 3D spheroids derived from recurrent ovarian cancer patients." (PMID 36142803, 2022). "In ovarian cancer, important hormones using the extracellular signal-regulated kinase (ERK) pathway (e.g., gonadotropins and gonadotropin-releasing hormones) activate the KRAS-BRAF-MEK axis, and consecutively, ERK which can then activate transcription factors, including myc or elk-1." (PMID 32429466, 2020). "Finally, to determine if the genes that display altered mRNA expression levels in ovarian cancer patient samples (PIK3CA, TTN, RYR2, KMT2C, KRAS, PTEN, and ARID1A) have any clinical value, we checked the effect of their expression on recurrence and survival of patients with ovarian cancer." (PMID 32626534, 2020). "Finally, different molecular markers have low or high expression in Type I vs. Type II ovarian carcinomas, but are rarely totally expressed (PTEN mutation, PIK3CA, KRAS mutation, BRAF mutation) or totally absent in either Type I or Type II EOCs." (PMID 31973035, 2020). "Interestingly, simultaneous mutations of KRAS and BRAF did not occur in the tested ovarian carcinomas with the exception of one mucinous case." (PMID 19018267, 2008). "However, its favourable therapeutic index and high selectivity may outweigh its shortcomings in KRAS and BRAF mutant ovarian cancer." (PMID 19018267, 2008). "Notably, AZD compounds did not change the mRNA expression of BRCA1/BRCA2 in ovarian cancer cells; however, AZD8835 could downregulate BRCA1/BRCA2 mRNA in KRAS-mutated OVCAR-8 cell via ERK signaling." (PMID 32194423, 2020).
ovarian carcinoma (continued). "Interestingly, co-amplification of KRAS and MAPK1 almost absent in the tested type II ovarian carcinomas, except one case." (PMID 23820584, 2013). "Interestingly, co-amplification of KRAS and MAPK1 seemed to be absent in the type II ovarian carcinomas tested, except one case." (PMID 23820584, 2013).
pancreatic adenocarcinoma (241 papers, 1994 to 2026). "In this phase I study, we test a pooled synthetic long peptide vaccine targeting the six KRAS mutations (G12V, G12A, G12R, G12C, G12D, G13D) with ipilimumab and nivolumab in resected pancreatic adenocarcinoma." (PMID 41667470, 2026). "The most commonly mutated residues in RAS-driven cancers included Gly12, Gln61, and Gly13, with KRAS mutations at codon 12 being particularly dominant in pancreatic adenocarcinomas and other exocrine pancreatic carcinomas." (PMID 41170373, 2025). "KRAS mutations are found in over 90% of conventional pancreatic adenocarcinomas, indicating that the KRAS pathway is heavily associated with invasion, whereas GNAS mutations are less commonly identified." (PMID 40002298, 2025). "In the pancreatic adenocarcinoma dataset of TCGA consortium, 131 of 140 patients harboring KRAS mutations were clonal (KRASG12mut), whereas others (9/140; 6.4%) had subclonal mutations at codons 12 and 6138." (PMID 39779977, 2025). "Pancreatic adenocarcinoma, for instance, is frequently driven by mutations regulating cell division (KRAS)." (PMID 40283189, 2025). "Our analysis showed that pancreatic adenocarcinoma specimens with wild-type KRAS status were 3.5 times more likely to have a GNAS mutation." (PMID 40002298, 2025). "KRAS mutations are predominantly found in pancreatic adenocarcinoma, colon adenocarcinoma, and rectal adenocarcinoma, whereas NRAS mutations are more common in skin cutaneous melanoma, anaplastic thyroid carcinoma, and follicular thyroid carcinoma." (PMID 41170373, 2025). "Among patients with KRAS wild-type pancreatic adenocarcinoma (representing 10% of all cases), 30% harbor BRAF mutations, accounting for 3% of all PAC." (PMID 41367868, 2025). "Though KRAS-G12C mutations are the most frequent in tumors of lung origin, it is also present in other solid tumors as well like colorectal or pancreatic adenocarcinomas." (PMID 38278976, 2024). "The KRAS gene exhibits a high mutation rate among all cancers, and is particularly associated with 78.7% of pancreatic adenocarcinoma (PAAD), 20.1% of lung adenocarcinoma (LUAD), and 49.7% of colorectal adenocarcinoma (COAD)." (PMID 39456601, 2024). "Most pancreatic adenocarcinomas (PDACs) harbor activation mutations of KRAS, which activates the PI3K/AKT signaling pathway." (PMID 38920688, 2024). "KRAS is one of the most commonly mutated driver oncogenes in lung, colorectal and pancreatic adenocarcinomas." (PMID 38278976, 2024). "KRAS mutations are observed in up to 20% of all human cancers and drive tumorigenesis in the 3 most lethal cancers in the United States, including adenocarcinomas of the pancreas (PAAD: 80%–90%), colon (COAD: 40%–50%), and lung (LUAD: 30%–40%)." (PMID 39287991, 2024). "In another experiment, an injection of the medication inside the peritoneum led to the regression of KRAS-mutated pancreatic adenocarcinoma xenografts compared to control animals, in a dose-dependent fashion." (PMID 37569406, 2023). "In pancreatic adenocarcinoma, KRAS mutations were found in 85.8% of cases, of which Q61R mutations were found in 1.2%, which was very rare with a frequency of about 1.0% of all PDAC cases." (PMID 37773552, 2023). "The relevance of KRAS mutation alleles to clinical outcome remains inconclusive in pancreatic adenocarcinoma (PDAC)." (PMID 37609177, 2023). "Recently, similar data were published from patients with pancreatic adenocarcinoma harboring the KRAS G12C mutation." (PMID 36836752, 2023). "To establish a suitable KRASG12R-driven model, we engineered a dsRed::KRASG12R-ARTi transgene and the dox-inducible ARTi-shRNAmir into KRASG12C-dependent MIA PaCa-2 pancreatic adenocarcinoma cells and subsequently knocked out endogenous KRAS alleles." (PMID 37552050, 2023).
pancreatic adenocarcinoma (continued). "Other cancer genes with high mutation frequencies include KRAS (mutated in 84%) of pancreatic adenocarcinomas and PTEN (67%) of uterine corpus endometrial carcinomas, and JAK2 (75%) of myeloproliferative neoplasms." (PMID 37550388, 2023). "Preclinical data combining SHP2 and ERK2 inhibition in KRAS-mutated pancreatic adenocarcinoma showed synergy and the triggering of apoptosis in vitro." (PMID 37569406, 2023). "The heatmaps showed that CIB1 is widely expressed in pancreatic adenocarcinoma cell lines, in which highly frequent KRAS mutation was also observed." (PMID 37187730, 2023). "Pancreatic adenocarcinoma, the seventh leading cause of cancer-related deaths worldwide, is considered the most KRAS-addicted cancer." (PMID 35971826, 2022). "Among KRAS mutations in pancreatic adenocarcinoma, residue G12 mutations (94%) predominate, while G13 and Q61 mutations (1.2 and 2.4%, respectively) are rare." (PMID 35045886, 2022). "In pancreatic adenocarcinoma, the three most common subtypes of KRAS mutations mRNA (i.e., G12D, G12V, and G12R) were examined." (PMID 35486030, 2022). "Mucinous adenocarcinomas of the appendix and pancreatic adenocarcinomas are the cancers with the highest frequency of missense mutations in KRAS, above 80%." (PMID 35120522, 2022). "For KRAS, under more restrictive assumptions, we observed evidence for a trade-off between functional and immune fitness for hotspot mutations in pancreatic adenocarcinoma, where KRAS is typically mutated." (PMID 35545680, 2022). "The most frequent genetic alteration in pancreatic adenocarcinoma, which is present in 70–95% of patients, is KRAS mutation." (PMID 35454771, 2022). "Approximately 95% of pancreatic adenocarcinoma patients are positive for KRAS mutation on endoscopy-guided or transcutaneous biopsy." (PMID 35454771, 2022). "KRAS is the most frequently mutated oncogene (95%) in pancreatic adenocarcinoma with a causal role in cancer initiation, propagation and maintenance." (PMID 34282051, 2021). "One example of a public neoantigen corresponds to the mutation of G12D on KRAS, which is frequently found in pancreatic adenocarcinoma, colon adenocarcinoma, non-small cell lung, and colorectal cancer." (PMID 34321091, 2021). "Given that pancreatic adenocarcinoma has both the highest frequency of KRAS mutations and EFR3A amplification, we focused on this cancer." (PMID 34504076, 2021). "Conversely, the expression levels of CCND1, DUSP2, ETS2, JUN, and RALGDS were decreased in lung and pancreatic adenocarcinomas with KRAS mutations." (PMID 33982211, 2021). "In sum, the EFR3A complex appears to be preferentially upregulated in KRAS-mutant pancreatic adenocarcinoma, which is associated with a worse clinical outcome." (PMID 34504076, 2021). "The fusions involved a variety of genes that have been shown to contribute to MAPK signaling, thus likely phenocopying the effect of activating KRAS point mutations that are present in pancreatic adenocarcinoma in >90% of cases." (PMID 33441414, 2021). "As the KRAS oncogene is mutated in > 95% of pancreatic adenocarcinomas, inhibition of signaling pathway downstream of KRAS is considered to be an attractive therapeutic approach." (PMID 32073727, 2020).
pancreatic adenocarcinoma (continued). "Consistently, analysis of the TCGA database demonstrates that high expression of PTPN2 is significantly associated with poor prognosis of patients with KRAS-mutant pancreatic adenocarcinoma." (PMID 33122197, 2020). "With over 90% pancreatic adenocarcinomas harbor oncogenic mutations in KRAS, identification of downstream effectors essential for KRAS-mediated tumorigenicity and drug resistance can lead to new targets of intervention for this intractable disease." (PMID 31296870, 2019). "Of the other frequent mutations, four mutations altered KRAS amino acid G12, primarily affecting colorectal, lung and pancreatic adenocarcinomas." (PMID 30412573, 2018). "For example, in LUAD, higher Treg infiltration was seen in samples harboring oncogenic KRAS mutation (G12V/D), whereas the same mutation in pancreatic adenocarcinoma (PAAD) correlated with high infiltration of CD8+, CD4+ T cells, and Neutrophils." (PMID 30622534, 2018). "KRAS performs an essential function in normal tissue signaling, while KRAS gene mutations are present in over 90% of the cases of pancreatic adenocarcinoma." (PMID 29474889, 2018). "The most frequently detected KRAS mutations were G12D (40.7%) and G12V (31.1%), which is consistent with the most common mutations identified through somatic testing of pancreatic adenocarcinoma tumors." (PMID 29228650, 2017). "Activating mutations of KRAS are nearly ubiquitous in pancreatic adenocarcinomas occurring in greater than 90% of cases." (PMID 27835861, 2017). "It is important to note that oncogenic KRAS mutations that are present in >90% of pancreatic adenocarcinomas are already detectable in precursor lesions, including early preinvasive intraepithelial neoplasia." (PMID 29156578, 2017). "KRAS gene mutations are considered the main cause of pancreatic adenocarcinoma onset together with hyperactivation of the Shh signaling pathway." (PMID 24878567, 2014). "The aim of this study was to use zebrafish to explore in vivo the tumorigenic action of a constitutively active mutant version of the oncogene KRAS, implicated in several types of pancreatic adenocarcinoma." (PMID 24878567, 2014). "Point mutations of the amino acid residue at position 12 of KRAS protein (G12V and G12D) are the most frequent changes found during the first stages of pancreatic adenocarcinoma." (PMID 24878567, 2014). "The highest incidence of KRAS mutations are found in adenocarcinomas of the pancreas (90%), with activating point mutations in codon 12 of KRAS to be the most common oncogene alterations." (PMID 25361007, 2014). "Codon 12 is the most common site for KRAS gene mutation in pancreatic adenocarcinoma with most being c." (PMID 23119210, 2012). "Mutations involving the Kirsten rat sarcoma viral oncogene homolog (KRAS) gene are present in the vast majority of pancreatic adenocarcinomas (more than 90%) and less frequently in pulmonary adenocarcinoma (15–30%)." (PMID 23119210, 2012). "In this paper, we used the identification of a KRAS mutation as a molecular signature of a metastatic pancreatic adenocarcinoma to the lung and thus show that this technique can be used to identify site of origin of metastatic carcinoma." (PMID 23119210, 2012). "The most frequent tumor to have a KRAS mutation is pancreatic adenocarcinoma which is present in more than 90% of the cases." (PMID 23119210, 2012).
pancreatic adenocarcinoma (continued). "Moreover, our in vitro and in vivo findings in pancreatic adenocarcinoma—a tumor type with one of the highest KRAS mutation rates—further indicate that COA4 knockdown suppresses metastasis." (PMID 40936169, 2025). "A major driver of pancreatic adenocarcinoma is mutations in KRAS, present in over 90% of cases." (PMID 40884689, 2025). "Over the years oncogenic addiction has been documented for KRAS mutants, whereby lung and pancreatic adenocarcinoma cell lines harboring KRAS mutations have been classified as KRAS-dependent or KRAS-independent on the basis of KRAS shRNA knockdown resulting in apoptosis." (PMID 41002380, 2025). "As expected, human PanNETs and MAP model tumors exhibit distinct transcriptional programs from those found in the KRAS-driven pancreatic adenocarcinoma KPC model, including those associated with inflammatory response, allograft rejection, NFkB, STAT3, and KRAS pathways." (PMID 38609433, 2024). "KRAS G12C accounts for approximately 1–2% mutations in pancreatic adenocarcinomas." (PMID 37366887, 2023). "KRAS G12D is the most common KRAS mutation in pancreatic adenocarcinoma (45–50%)." (PMID 37366887, 2023). "Similarly, the finding that 85.7% of pancreatic ASC had mutations in the KRAS gene confirms its resemblance to pancreatic adenocarcinoma, where nearly 100% have KRAS mutations." (PMID 35871081, 2022). "Additionally, the relatively common cancer with the highest prevalence of RAS mutations in pancreatic adenocarcinoma, which has a KRAS mutation in nearly 90% of all sequenced samples." (PMID 34645806, 2021). "Whether this reflects a hyper-dependency on KRAS mutations in pancreatic adenocarcinoma, or some unique feature of pancreatic tumorigenesis remains to be elucidated." (PMID 34504076, 2021). "KRAS is mutated in about 30% of all human tumors, but it could reach more than 90% in certain cancer types such as pancreatic adenocarcinoma." (PMID 33777798, 2021). "The phosphoinositide 3-kinases (PI3k)/phosphatase and tensin homolog (PTEN)/protein kinase B (Akt)/mammalian/mechanistic target of rapamycin complex 1 (mTORC1) is another key pathway activated in pancreatic adenocarcinomas and the latter pathway is associated with KRAS." (PMID 34901697, 2021). "For example, in NSCLC, KRAS mutations account for 20.4% of KRAS, and the dominant substitution is G12C (glycine (GGT) to cysteine (TGT)), while KRAS mutation accounts for up to 67.6% of KRAS in pancreatic adenocarcinoma, and KRAS (G12D) is the dominant mutant subtype." (PMID 34776511, 2021). "Of note, over 90% pancreatic adenocarcinoma patients burden mutations in KRAS." (PMID 33819918, 2021). "Interestingly, G12D mutation is the most common mutation in pancreatic adenocarcinoma, with approximately 90% of patients harboring a mutation in KRAS." (PMID 33086698, 2020). "We tried to identify the KRAS5−6/8−14 G12V spliced and the KRAS5−14 G12V non-spliced epitope candidates through the MS measurement of the HLA-I immunopeptidomes of the SW480 pancreatic adenocarcinoma cell line, which expresses the HLA-A*02:01 complex and the KRAS G12V mutated protein." (PMID 31803176, 2019). "Finally, we assessed the expression of SQSTM1 and CDH1 in human pancreatic adenocarcinoma where 90% of tumors harbor KRAS mutations." (PMID 30782064, 2019). "We first tested whether expression of the human orthologs of the 80 confirmed Drosophila hits correlate with the survival of patients with pancreatic adenocarcinomas, a tumor-type with frequent KRAS activating mutations." (PMID 30325918, 2018). "In 80-90% of pancreatic adenocarcinomas the KRAS gene on chromosome 12 is mutated." (PMID 27602750, 2017).